PXN (paxillin)
Diseases named in the same sentence as PXN in open-access papers (continued):
Sharing a sentence is not in itself a finding about the gene and the disease.
melanoma (39 papers, 2008 to 2026). A malignant, usually aggressive tumor composed of atypical, neoplastic melanocytes. "In addition, the release of ADAM10 in EVs by melanoma cells was shown to be linked to a paxillin/integrin interaction and a subsequent shift to lipid rafts, supporting the suggested mechanism for ADAM8 exosomal release." (PMID 35216088, 2022). "Moreover, paxillin mutations have been implicated in the poor prognosis of various invasive tumors, including breast, lung, and melanoma, suggesting that paxillin is important for controlling cell migration and invasion in living tissues." (PMID 22194823, 2011). "Suppressing the interaction between FAK and paxillin in melanoma cells can inhibit invadopodia-mediated matrix degradation, thereby inhibiting cell invasion and metastasis." (PMID 40861820, 2025). "Quercetin, in turn, was demonstrated to reduce melanoma cells migration through inhibition of FAK-paxillin-Akt expression and the STAT3 signaling pathway." (PMID 40364408, 2025). "Another study also showed that reducing the expression of FAK and its downstream reactive protein paxillin inhibited the EMT process in melanoma cells, thereby inhibiting the migratory activity of tumor cells." (PMID 37175948, 2023). "To visualize focal adhesions in vivo, we used the zebrafish MiniCoopR system to generate zebrafish melanoma tumors expressing zebrafish Paxillin, a core focal adhesion protein, tagged with EGFP." (PMID 36723624, 2023). "An increased number of focal adhesions revealed by phospho‐paxillin staining characterized melanoma cells expressing miR‐143‐3p or miR‐145‐5p or melanoma cells upon BRAF pathway inhibition." (PMID 35156321, 2022). "We also assessed the expression of PXN in a panel of 163 patient-derived melanoma cells exhibiting different levels of MITF." (PMID 33438577, 2021). "Quantification revealed that FAK enrichment at FAs, identified by P-paxillin staining, increased by 66% in metastatic melanoma cells compared to HEMs." (PMID 33919725, 2021). "We observed that this strategy blocks FAK–paxillin interaction and inhibits both migration and the proteolytic activity of invadopodia in human melanoma cells." (PMID 33919725, 2021). "To visualize if these mutations altered FAK localization at FAs, we analyzed paxillin localization by immunofluorescence, a marker of FAs, in FAK-depleted A375 melanoma cells expressing FAK-WT-GFP or FAK-I936/I998-GFP." (PMID 33919725, 2021). "Our data showed that the number of paxillin-positive dots was induced in both MITF-KO and miR-MITF cells as compared to controls (g h) and paxillin expression was inversely correlated with MITF expression in melanoma tissues and cell lines." (PMID 33438577, 2021). "Molecules such as p130Cas and paxillin are involved in the GD3-mediated signaling pathways of melanoma cells." (PMID 34064863, 2021). "The biological roles of individual GSLs was studied in melanoma cell lines and allowed researchers to demonstrate major differences: serum-induced phosphorylation p130Cas and paxillin was increased in GD3+ cells compared to GD2+ or GM3+ cells." (PMID 32192217, 2020). "GD3 activates growth factor receptors that are combined with adhesion signals by integrins, resulting in the activation of downstream signaling molecules such as Akt, p130Cas and paxillin, and finally in increased growth and invasion of melanoma cells." (PMID 32192217, 2020). "To go inside the transduction pathway of movement inhibited by 2-DG, we evaluated the positivity of melanoma cells for Paxillin, a protein expressed by focal adhesions of cells." (PMID 31454998, 2019). "Our results demonstrate that the HLA-B,C-specific mAb B1.23.2 can significantly reduce the motility and Paxillin expression in both A375-M6 and FO-1β2 melanoma cells." (PMID 31454998, 2019). "Level of Paxillin phosphorylation in A375-M6 melanoma cells treated with 2-DG was dramatically reduced." (PMID 31454998, 2019).
melanoma (continued). "Molecules involved in GD3-mediated signaling pathways, such as p130Cas and paxillin, are potential targets for melanoma treatment." (PMID 29773994, 2018). "Our results showed for the first time that genistein influences the FAK/paxillin pathway in melanomas." (PMID 28423510, 2017). "Noticeable, many of the protein networks involved in these pathways have been reported to be upregulated in many human cancers and can predict invasiveness, these include Rab7 in agreement with another study in melanoma, paxillin and Atg proteins." (PMID 28415719, 2017). "The present study determined the participation of paxillin in the reported effects of 4-HC and analyzed the role of paxillin in the formation of melanoma metastases." (PMID 18492274, 2008). "Analysis of paxillin expression by immunoblotting showed that B16-F10 melanoma cells normally express α and β isoforms of paxillin (control lane)." (PMID 18492274, 2008). "We also studied the importance of paxillin in metastasis by transfecting melanoma cells with paxillin-siRNA." (PMID 18492274, 2008). "Paxillin is overexpressed in numerous cancers, including melanoma." (PMID 41492449, 2026). "p130Cas and paxillin orchestrate cellular proliferation and invasion in melanoma cells." (PMID 38791186, 2024). "We overexpressed mammalian GFP-FAK in mouse YUMM1.7 melanoma cells and determined whether we could detect a corresponding increase in pY118-Paxillin in cells in vivo." (PMID 36723624, 2023). "In glioma, melanoma, and small cell lung cancer (SCLC) cells, GD2 expression has been linked to increased cell adhesion via phosphorylation of focal adhesion kinase (FAK) and adapter proteins involved in adhesion such as paxillin or p130 Cas." (PMID 37373053, 2023). "It is known that activation of the FAK/paxillin pathway and mitogen-activated protein kinases (MAPKs) signaling may serve as a possible indicator of melanoma metastasis." (PMID 37687080, 2023). "Using mouse melanoma tumors expressing wildtype Paxillin, which already exhibit low levels of Paxillin Y118 phosphorylation in vivo, indeed we found that a significantly higher amount of CRKII and DOCK180/RacGEF interacted with wildtype Paxillin in cells in vivo versus cells in culture." (PMID 36723624, 2023). "The inhibition of FAK-paxillin interaction may be an effective strategy to inhibit invadopodia-mediated matrix degradation to inhibit the invasion and metastasis of melanoma cells." (PMID 37175948, 2023). "The AKT, p130Cas, and paxillin enhance tumorigenesis in certain cancers like melanomas." (PMID 36313783, 2022). "Therefore, RNAi knockdown of p130Cas and/or paxillin strongly suppressed GD3-expressing melanoma growth." (PMID 34064863, 2021). "To further check whether the paxillin clusters formed on galectin-8 substrates contain integrin β3, we used B16 melanoma cells stably expressing GFP-integrin-β3." (PMID 33722978, 2021). "Next, to investigate whether the inhibition of FAK–paxillin interactions affects melanoma invasion, siFAK-treated A375 melanoma cells expressing wild-type FAK-GFP or FAK-I936/I998-GFP were plated on Cy3-gelatin and labeled for actin and cortactin." (PMID 33919725, 2021). "Therefore, we analyzed the Phalloidin and Paxillin phosphorylation staining in A375-M6 and FO-1β2 melanoma cells following a 24 h incubation with the HLA-B,C-specific mAb B1.23.2." (PMID 31454998, 2019). "RNAi blocking of p130Cas and/or paxillin strongly suppressed melanoma growth." (PMID 29773994, 2018). "In melanoma, activated integrin β1 is required for the attachment of metastatic melanoma cells to the vascular basement membrane via regulating the downstream FAK/paxillin pathway, and this integrin helps the extravasation of metastatic melanoma cells into the liver and lungs." (PMID 29703238, 2018).
melanoma (continued). "The fact that metastatic potential of B16-F10 cells is reduced by decreasing paxillin expression support the hypothesis that paxillin facilitates metastasis and emphasize the importance of paxillin as an inducer of melanoma metastasis." (PMID 18492274, 2008). "Interestingly, the interaction network identified additional kinases that are involved in cancer progression but that have not been previously associated with melanoma, such as paxillin, PLCG1 and TEC." (PMID 32098410, 2020). "Similarly, levels of phospho-paxillin are much higher in melanoma cell lines than in melanocytes." (PMID 18492274, 2008). "In melanoma, inhibition the FAK-paxillin interaction has been shown to be an effective therapeutic strategy, as demonstrated in several reports using site-directed mutagenesis, dominant-negative constructs, and therapeutic peptides." (PMID 41492449, 2026). "For instance, in melanomas, AKT, p130Cas, and paxillin drive carcinogenesis and migration, potentially mediated by Src family proteins." (PMID 41190221, 2025). "Knockdown experiments targeting gangliosides GM3 and GD3 resulted in reduced cell growth and migration in melanoma cells, accompanied by decreased expression of FAK and paxillin." (PMID 38791186, 2024). "Regardless of ganglioside siRNA presence, both quercetin-treated and untreated melanoma cells showed consistent decreases in FAK, paxillin, and p-Akt protein levels." (PMID 38791186, 2024). "CLPS inhibits metastasis of the melanoma cell line, B16F10, to lungs by blocking the signaling pathway involving β1 integrin, FAK and paxillin." (PMID 33916178, 2021). "Signaling kinases and adaptor molecules (p130Cas, paxillin, FAK) have been shown to respond to GD3 upregulation by conferring malignant phenotypes in melanoma and osteosarcoma." (PMID 28537895, 2017). "JNK interacts with and phosphorylates paxillin leading to an increased formation of invadopodia in gliomas, and JNK inhibition in melanoma by α-solanine significantly reduces cell migration and invasion." (PMID 28107182, 2017). "In addition, the β1 integrin subunit was found to be required for melanoma cell adhesion to ECs, mainly through the FAK/paxillin pathway, and for the extravasation of melanoma cells at metastasis sites (mainly in liver and lung)." (PMID 39866233, 2025). "Reduction in F-actin stress fibers by 54% to 28% compared to control; reduction in melanoma adhesion to fibronectin by 35% to 64%; reduction in phosphorylation of FAK by 50% to 65% and paxillin by 55% to 70% at various concentrations; reduction in focal adhesions per cell by 36%." (PMID 39594665, 2024). "Thus, we generated melanoma tumors in mice by injecting C57BL/6J mice with YUMM1.7 cells, a highly metastatic murine melanoma cell line, expressing wildtype mammalian Paxillin with a self-cleavable (T2A) GFP tag." (PMID 36723624, 2023). "To date, TRPV2 is the only Ca2+‐permeant channel reported as directly participating in paxillin‐rich adhesive structures, revealing a mechanism through which TRPV2 could boost melanoma tumor cell invasiveness." (PMID 36744297, 2023). "Interestingly, it has been observed that low concentrations of genistein can activate the FAK/paxillin and MAPK signaling pathways, leading to enhanced invasion and migration of melanoma cells." (PMID 37687080, 2023). "The effects of apigenin on A2058 and A375 melanoma cells have been evaluated, consistent with our studies, apigenin effectively inhibited the cell migration of HeLa and C33A cells via inactivation of the FAK signaling (FAK, paxillin, and integrin β1) pathways." (PMID 35406599, 2022). "This showed that expression of PXN was specifically induced in MITFlow melanoma cell lines and displayed a negative correlation with MITF expression." (PMID 33438577, 2021). "However, little is currently known about genistein's effects on melanoma cells, especially its anti-metastatic potential on the FAK/paxillin pathway." (PMID 28423510, 2017).
melanoma (continued). "Transfection produced a modest reduction on metastatic potential, indicating that: i) paxillin plays a role as inducer of melanoma metastasis; and ii) paxillin downregulation is not sufficient to explain the antimetastatic effect of 4-HC." (PMID 18492274, 2008). "Collagen type IV was shown to promote adhesion, migration, and spreading of melanoma cells via interaction with chondroitin sulfate proteoglycan via CD44 or β1 integrin involving the signaling cascades related to p(Tyr127)FAK and paxillin, PI3-kinase, and protein kinase C (PKC)." (PMID 34440617, 2021). "However, on fibronectin-coated substrates, B16 melanoma cells formed focal adhesions enriched with GFP-integrin-β3, whereas paxillin-rich clusters formed on galectin-8 did not contain GFP-integrin-β3, and were associated with short actin filaments, rather than with the ends of stress fibers." (PMID 33722978, 2021).
lung cancer (37 papers, 2006 to 2025). A malignant neoplasm involving the lung. "Paxillin mutations were shown to play a role in mitochondrial dynamics and influence lung cancer progression." (PMID 34013964, 2021). "Enhanced expression and phosphorylation of paxillin has been linked to therapy resistance in other cancer cell types, such as lung cancer." (PMID 33438577, 2021). "Our lab has studied the effect of activating mutations of paxillin on mitochondrial dynamics in lung cancer." (PMID 26980710, 2016). "Mutations in paxillin are shown to be associated with lung cancer; and the differential expression of paxillin is associated with various forms of cancer and other diseases such as Alzheimer’s and inflammation." (PMID 26928467, 2016). "Additionally, survival analysis revealed that high PXN expression was associated with a poor prognosis in patients with lung cancer." (PMID 39034411, 2024). "Paxillin has been shown to be highly expressed in many malignant tumors and is frequently associated with progression and poor patient outcomes, as seen in gastric cancer, lung cancer, esophageal cancer, and colorectal cancer." (PMID 37958964, 2023). "Interestingly, paxillin mutations associated with lung cancer were observed in the unstructured segments, particularly the regulatory region of LD2 and masking region of LD4." (PMID 26928467, 2016). "Expression of PXN is associated with adverse pathologic characteristics in hepatocellular carcinoma; PXN protein level is correlated with advanced clinical stage and distant metastasis in salivary adenoid cystic carcinoma; amplification of PXN is frequently observed in high risk lung cancer." (PMID 24180516, 2013). "Importantly, mutation and misregulation of paxillin correlate with metastatic potential in some human breast and lung cancers, suggesting that it may be involved in regulating ECM invasion as well." (PMID 22194823, 2011). "To determine the potential clinical relevance of CD155 and PXN overexpression, we performed IHC staining for CD155 and PXN in a tissue microarray of tumor samples from patients with lung cancer." (PMID 40634277, 2025). "Taken together, A5 Nb selectively disrupts focal adhesion dynamics by downregulating PXN in CD155-overexpressing lung cancer cells, leading to impaired cell adhesion and migration." (PMID 40634277, 2025). "In our study, A5 Nb treatment did not alter ERK or AKT phosphorylation but significantly reduced PXN expression in CD155-overexpressing lung cancer cells." (PMID 40634277, 2025). "In summary, our study revealed that CXCL5 overexpression can upregulate PD-L1 via PXN/AKT phosphorylation in lung cancer." (PMID 39034411, 2024). "In a study of lung cancer, the expression of paxillin in cancer tissue was higher than in normal lung tissue, and the somatic mutation rate was 9.4%, of which the most common point mutation (A127T) enhanced the growth and invasion ability of lung cancer cells." (PMID 37175948, 2023). "A newly developed novel ST inhibitor, Lith-O-Asp, can inhibit lung cancer cell metastasis by inhibiting FAK/paxillin signaling and expressing antiangiogenic factors and is considered a potential antimetastatic therapy." (PMID 37175948, 2023). "Highly expressed PXN was linked to poor PFS, OS, and PPS in gastric cancer (P < 0.001) and poor PS (P < 0.001), OS (P < 0.001), and PPS (P = 0.01) in lung cancer." (PMID 34135128, 2021). "The findings presented in this study suggest that nWASP inhibition in lung cancer cell types does in fact alter cell morphology with respect to the level of paxillin-rich membrane structures the cells are able to produce." (PMID 28351346, 2017). "EL decreased phosphorylation of FAK and its downstream targets, Src, paxillin, and decreased mRNA expression of cell motility-related genes, RhoA, Rac1, and Cdc42 in lung cancer cells." (PMID 28068967, 2017).